OPTN (optineurin)
Diseases named in the same sentence as OPTN in open-access papers (continued):
Sharing a sentence is not in itself a finding about the gene and the disease.
glaucoma (continued). "However, no OPTN mutation has been reported to cause either glaucoma or ALS, and no E50K-linked case of ALS has been reported." (PMID 33723228, 2021). "However, because of endogenous OPTN or the overexpression of E50K OPTN, it remains unclear whether the mechanisms of this induction are comparable to the situation seen in glaucoma." (PMID 33723228, 2021). "Indeed, the role of Optineurin in glaucoma pathogenesis requires further study, particularly, whether its overexpression can be a protective measure in retina upon oxidative stress." (PMID 32340220, 2020). "Interestingly, mutations in OPTN, encoding optineurin, are associated with both ALS and glaucoma." (PMID 29875767, 2018). "In this review, we summarize the role of optineurin in cellular mechanisms implicated in neurodegenerative disorders, including neuroinflammation, autophagy, and vesicular trafficking, focusing in particular on the consequences of expression of mutations associated with ALS and glaucoma." (PMID 29875767, 2018). "Interestingly, 661W cells show induction of cell death by two glaucoma-associated mutants of OPTN but not by wild-type OPTN or by an ALS-associated mutant E478G." (PMID 29951055, 2018). "Although E50K and M98K mutants of OPTN when expressed in 661W (this study) and RGC-5 cells induce more cell death than wild type OPTN, some other glaucoma-associated mutants (H26D, H486R, T202R, E322K) did not induce this cell death in 661W (this study) as well as RGC-5 cells." (PMID 29203899, 2017). "Interestingly, we found that cOPTN3 can also be observed in the E50K-transfected cells without additional stimuli, but is not observed in cells expressing OPTN bearing other glaucoma-associated mutations." (PMID 24983867, 2014). "Furthermore, the demonstrations that optineurin is an aggregation-prone protein and that the foci formation is microtubule-dependent bear similarities to features documented in neurodegenerative diseases, supporting a neurodegenerative paradigm for glaucoma." (PMID 20161783, 2010). "It has been suggested that reduction in expression of optineurin due to mutation in the coding region, rather than altered function may contribute to the development of glaucoma." (PMID 19340308, 2009). "However, later studies reported no glaucoma causing mutations in OPTN among Caucasian and Japanese POAG patients." (PMID 19145250, 2009). "The mechanistic role of OPTN in the pathogenesis of glaucoma remains unclear." (PMID 19096531, 2008). "Through literature review, several key glaucoma-related genes were identified, including MYOC, TBK1, COL1A1, COL1A2, FOXC1, LRP2, OPTN, and TEK." (PMID 40808675, 2025). "In this review, we summarize the current understanding of the role of optineurin in ALS, glaucoma, and also other neurodegenerative diseases, focusing on autophagy, vesicular trafficking, and neuroinflammation." (PMID 29875767, 2018). "myocilin (MYOC), optineurin (OPTN), WDR36 and neurotrophin-4 (NTF4) in primary open angle glaucoma (POAG) and CYP1B1 and LTBP2 in congenital and developmental glaucomas." (PMID 21150032, 2011). "Two of these high penetrance glaucoma genes, MYOC and OPTN, are responsible for around 4% of POAG cases overall." (PMID 21321670, 2011). "Disease-associated sequence variants in three genes, myocilin (MYOC, GLC1A), optineurin (OPTN,GLC1E), and WD repeat domain 36 (WDR36, GLC1G), have been described in POAG and other types of glaucoma." (PMID 19096531, 2008). "MYOC, OPTN, WDR36, and CYP1B1 have all been identified in a relatively small percentage of patients with various types of glaucoma, and it remains possible that these genes are abnormal with a small percentage of PEG patients." (PMID 18246027, 2008). "For example, individuals carrying a mutation in their MYOC, OPTN, or other glaucoma Mendelian genes are likely to have early-onset glaucoma (<40 years of age), yet, up to one-fifth of individuals with mutations may not have manifest glaucoma, even in older age." (PMID 40168146, 2025).
glaucoma (continued). "Taken together, these studies suggest multiple links between OPTN and NF-κB pathway, although not yet clearly characterized for glaucoma." (PMID 33953963, 2021). "Disease mutations in OPTN linked to primary open-angle glaucoma (POAG) cause aberrant foci formation in the absence of stimuli, which correlates with the ability of OPTN to inhibit signalling." (PMID 32376785, 2020). "Whilst optineurin has not been well studied in relation to neurodegeneration, optineurin dysfunction is associated with several cellular mechanisms that are implicated in the pathogenesis of ALS and glaucoma." (PMID 29875767, 2018). "The ALS optineurin mutant E478G induced cell death specifically in motor neuron-like cells, compared to glaucoma mutants E50K or M98K, which did not affect cell survival." (PMID 29875767, 2018). "This review, therefore showcases the impact of optineurin dysfunction in ALS and glaucoma." (PMID 29875767, 2018). "How other mutants of OPTN that do not induce death of retinal cells in culture, contribute to glaucoma pathogenesis, is yet to be investigated." (PMID 29951055, 2018). "Hence, together these data indicate that optineurin is involved in the pathogenesis of ALS and glaucoma." (PMID 29875767, 2018). "Furthermore, disease alleles were observed for other autosomal dominantly inherited degenerative diseases of sensory function, including retinitis pigmentosa (SEMA4A, RP1), deafness (MYO1A), glaucoma (CYP1B1, OPTN, WDR36), and keratoconus (VSX1)." (PMID 25333069, 2014). "The E50K mutant but not wild type optineurin causes death of RGC, indicating thereby that this mutation causes glaucoma by directly inducing death of RGC." (PMID 20085643, 2010). "Recently, Park’s study had revealed that OPTN could regulate the expression of MYOC primarily through the control of mRNA stability, indicating that interaction exists between the two glaucoma genes." (PMID 19145250, 2009). "Optineurin (OPTN) is a protein that interacts with a series of events, including cell morphogenesis, vesicular trafficking, transcriptional regulation, and autophagy, and has been a genetic marker in normal tension glaucoma and primary open-angle glaucoma (POAG)." (PMID 40141848, 2025). "Regarding genetic glaucoma models, we considered the main hallmarks and limitations of DBA/2J, glutamate/aspartate transporter/excitatory amino acid carrier 1, myocilin, connective tissue growth factor, optineurin, purinergic receptor 2Y, caveolin 1, and endothelin-1 mice." (PMID 41227293, 2025). "Therefore, the defects in mitochondrial biogenesis mediated by oxidative stress in E50K OPTN may also play a role in RGC death and the development of glaucoma." (PMID 40385286, 2025). "Furthermore, additional genes can also exacerbate non-neurodegenerative disease phenotypes, such as glaucoma (optineurin, OPTN), Enterovirus-induced Type-1 diabetes (Peripherin, PRPH), leukemia, or cancer (TATA-box-binding protein-associated factor 15, TAF15)." (PMID 37566027, 2023). "Similarly, another glaucoma mutant, E50K, selectively induced ROS-associated-specific death of RGCs but not COS-1, HeLa or IMR32 cell lines, whilst overexpression of wild-type optineurin did not." (PMID 29875767, 2018). "Two glaucoma-associated mutants of OPTN, E50K and M98K, induced significantly more cell death than wild type (WT) OPTN selectively in 661W cells but an ALS-associated mutant of OPTN, E478G, did not induce cell death." (PMID 29203899, 2017). "The higher levels of optineurin in RGCs compared to brain might contribute to increased RGC death resulting in glaucoma with relatively little or no neuronal cell death elsewhere." (PMID 20085643, 2010). "However, unlike humans, OPTN-KO mice did not exhibit any symptoms resembling glaucoma and ALS." (PMID 27552911, 2016).
glaucoma (continued). "The same applies to glaucoma, where complex Mendelian and non-Mendelian genetic mechanisms coexist, with multiple loci, such as MYOC, OPTN, and TBK1, each contributing to the variability and progression of glaucomatous neurodegeneration." (PMID 39766826, 2024). "However, it is also possible that mutant optineurin acquires additional, non-physiological binding partners in ALS, and/or glaucoma, resulting in a toxic gain-of-function mechanism." (PMID 29875767, 2018). "However, expression of another glaucoma mutant, H486R, resulted in an altered interaction of optineurin with CYLD compared to wild-type, resulting in a lack of NF-κB inhibition, similar to studies in which optineurin was knocked out." (PMID 29875767, 2018).
amyotrophic lateral sclerosis (89 papers, 2010 to 2026). Amyotrophic lateral sclerosis (ALS) is a neurodegenerative disease characterized by progressive muscular paralysis reflecting degeneration of motor neurons in the primary motor cortex, corticospinal tracts, brainstem and spinal cord. "Mutations in optineurin have been linked with primary open-angle glaucoma, Paget’s disease of the bone, and amyotrophic lateral sclerosis (ALS)." (PMID 39996775, 2025). "The OPTN gene, which encodes the adaptor protein optineurin, is genetically linked to amyotrophic lateral sclerosis and frontotemporal dementia, diseases characterized by chronic microglial activation." (PMID 41226491, 2025). "Mutations in the human OPTN gene have been identified in several familial diseases, including amyotrophic lateral sclerosis (ALS) and glaucoma." (PMID 39762159, 2025). "Mutations in optineurin were found in amyotrophic lateral sclerosis, an adult-onset fatal neurodegenerative disease that targets motor neurons." (PMID 36829517, 2023). "Mutations in OPTN are linked to amyotrophic lateral sclerosis (ALS), a neurodegenerative disease caused by the gradual degeneration of motor neurons." (PMID 36595944, 2022). "OPTN, a causative gene of mitochondrial dysfunction-related amyotrophic lateral sclerosis (ALS) and glaucoma diseases, was shown to participate in PINK1/Parkin-mediated mitophagy by recruiting damaged mitochondria via its LIR." (PMID 32235615, 2020). "Mutations in optineurin leading to amyotrophic lateral sclerosis (ALS) result in impaired mitophagy." (PMID 30488644, 2019). "OPTN mutations are linked to amyotrophic lateral sclerosis, frontotemporal lobar degeneration, and normal-tension glaucoma; but it is also observed in protein inclusions present in Alzheimer's disease, Huntington's disease, and PD." (PMID 29867311, 2018). "Analysis of functionally linked amyotrophic lateral sclerosis proteins revealed recruitment of p62, ubiquilin-2, and optineurin to TDP-43 aggregates." (PMID 28724966, 2017). "Mutations in optineurin are associated with neurodegenerative diseases, including amyotrophic lateral sclerosis." (PMID 27552911, 2016). "More recently, mutations in optineurin have also been reported to associate with amyotrophic lateral sclerosis (ALS)." (PMID 25943884, 2015). "We report the cases of siblings with amyotrophic lateral sclerosis with homozygous deletions of the exon 5 mutation of the gene encoding optineurin, in whom brain computed tomography scans were followed up for more than 20 years." (PMID 22152722, 2011). "Intriguingly, OPTN mutations have also recently been identified in Japanese individuals from consanguineous marriages and with a familial form of amyotrophic lateral sclerosis (ALS)." (PMID 21112411, 2011). "MVIBD consists of two known Myosin VI binding sites fused in tandem, one from Optineurin, a protein that is associated with amyotrophic lateral sclerosis and a second from Disabled homolog 2 (DAB2), which has been associated with prostate cancer." (PMID 21390300, 2011). "For neurodegenerative diseases, optineurin (OPTN) regulates both NF-κB activation and apoptosis via linear ubiquitin binding, and the loss of this ability may lead to amyotrophic lateral sclerosis (ALS)." (PMID 37813853, 2023). "Finally, mutations in OPTN have been linked to primary forms of glaucoma as well as amyotrophic lateral sclerosis (ALS)." (PMID 36339819, 2022). "Optineurin is a gene associated with normal tension glaucoma and amyotrophic lateral sclerosis." (PMID 25943884, 2015). "Later on, certain mutations in OPTN were shown to cause amyotrophic lateral sclerosis." (PMID 24752605, 2014). "We conclude that a homozygous deletion-type mutation in the optineurin gene may be associated with widespread multisystem degeneration in amyotrophic lateral sclerosis." (PMID 22152722, 2011).
amyotrophic lateral sclerosis (continued). "Optineurin (OPTN) is associated with several human diseases, including amyotrophic lateral sclerosis (ALS), and is involved in various cellular processes, including autophagy." (PMID 37352136, 2023). "Optineurin mutations are associated with amyotrophic lateral sclerosis (ALS) and frontotemporal dementia (FTD), neurodegenerative diseases characterised by neuronal loss, neuroinflammation, and peripheral immune disbalance." (PMID 37481656, 2023). "Mutations in optineurin, a ubiquitin-binding adaptor protein, cause amyotrophic lateral sclerosis (ALS), a fatal neurodegenerative disease of motor neurons linked to chronic inflammation and protein aggregation." (PMID 35743272, 2022). "It was shown that amyotrophic lateral sclerosis (ALS)-associated optineurin mutations cause mitophagy disorders." (PMID 34638589, 2021). "OPTN is also a causative gene for amyotrophic lateral sclerosis (ALS) and primary open-angle glaucoma (POAG)." (PMID 34685685, 2021). "More recently, optineurin, mutations of which are associated with amyotrophic lateral sclerosis (ALS), was shown to trigger degradation of RIPK1 and its loss lead to axonal degeneration." (PMID 31131275, 2019). "Since then, optineurin has been implicated as a genetic risk factor in Paget’s disease of bone, familial and sporadic forms of amyotrophic lateral sclerosis (ALS) and Crohn’s disease." (PMID 29867991, 2018). "Later on, OPTN mutations were also identified in other human pathologies including Paget disease of bone, amyotrophic lateral sclerosis (ALS) and frontotemporal dementia (FTD), explaining the growing interest of the scientific community for this gene." (PMID 29692786, 2018). "More recently, mutations in optineurin were also reported to be associated with amyotrophic lateral sclerosis (ALS)." (PMID 24683533, 2014). "Disruptions in OPTN can interfere with mitophagy, potentially leading to the build-up of dysfunctional mitochondria and contributing to diseases such as amyotrophic lateral sclerosis (ALS) and glaucoma." (PMID 39859167, 2025). "Lastly, there is a rare mutation that involves a 2 base pair (bp) insertion into exon 6 of the OPTN gene (691_692insAG or 2bpIns-OPTN) that is associated with NTG and amyotrophic lateral sclerosis (ALS)." (PMID 41567509, 2025). "Furthermore, mitophagy is impaired in Alzheimer disease, and loss-of-function mutations in the mitophagy regulator TBK1 (TANK-binding kinase 1) and the receptor protein, optineurin, are associated with ALS (Amyotrophic Lateral Sclerosis)." (PMID 34844982, 2022). "OPTN and a key regulatory kinase, TBK1, both of which have been identified as genes linked to familial or sporadic amyotrophic lateral sclerosis, interact and are required for efficient mitophagy." (PMID 32556086, 2020). "Mutations associated with amyotrophic lateral sclerosis (ALS) appear in the proteins SOD1, FUS, TDP-43, and OPTN which become misfolded and aggregate." (PMID 30083092, 2018). "OPTN gene mutations have previously been associated with primary open angle glaucoma (POAG), amyotrophic lateral sclerosis (ALS) and Paget's disease of the bone." (PMID 26044960, 2015). "Optineurin is localized to pathological structures seen in several neurodegenerative diseases such as amyotrophic lateral sclerosis, Alzheimer’s disease, Parkinson’s disease, etc." (PMID 24752605, 2014). "Homozygosity mapping has power to identify a disease-causing gene in as few as 3 patients, and we have indeed identified the SLC34A2 gene in pulmonary alveolar microlithiasis and the OPTN gene in the amyotrophic lateral sclerosis both in 3 patients." (PMID 21106127, 2010). "OPTN is a known factor in dominant adult‐onset glaucoma and Amyotrophic Lateral Sclerosis (ALS)." (PMID 26740941, 2015).